FRMD8 (FERM domain containing 8)
Description:
Promotes the cell surface stability of iRhom1/RHBDF1 and iRhom2/RHBDF2 and prevents their degradation via the endolysosomal pathway. By acting on iRhoms, involved in ADAM17-mediated shedding of TNF, amphiregulin/AREG, HBEGF and TGFA from the cell surface. Negatively regulates Wnt signaling, possibly by antagonizing the recruitment of AXIN1 to LRP6.
Synonyms: iTAP; FKSG44; FLJ90369
Tractability: Antibody: UniProt places it where antibodies can reach, with high confidence; its Gene Ontology location is reachable by antibodies, with high confidence. PROTAC: ubiquitination databases record sites on it; its protein half-life has been measured.
Gene: Protein-coding gene on chromosome 11 (65,386,592 to 65,413,525, forward strand). Ensembl gene ENSG00000126391.
Subcellular location: Cytoplasm, cytosol; Cell membrane
Subcellular location (Human Protein Atlas): Centriolar satellite; Plasma membrane; Cytosol; Nucleoplasm
Gene Ontology:
Molecular function: protein binding
Biological process: positive regulation of tumor necrosis factor production; negative regulation of canonical Wnt signaling pathway
Cellular component: cytosol; plasma membrane
Genetic constraint (gnomAD): Loss-of-function variants: 36 observed, 41.42 expected, observed/expected ratio (o/e) 0.87, 90% interval 0.67 to 1.15. The upper end of that interval is the gene's LOEUF score, 1.15, which puts it in group 5 of 6, group 1 being the genes least tolerant of losing a copy. Missense variants: 582 observed, 577.19 expected, observed/expected ratio (o/e) 1.01, 90% interval 0.94 to 1.08. Synonymous variants: 241 observed, 242.83 expected, observed/expected ratio (o/e) 0.99, 90% interval 0.89 to 1.1.
Homologues: Orthologues: chimpanzee FRMD8 (99% identical), macaque FRMD8 (97% identical), guinea pig FRMD8 (89% identical), dog FRMD8 (88% identical), mouse Frmd8 (88% identical), pig FRMD8 (87% identical), rat Frmd8 (87% identical), rabbit FRMD8 (76% identical), tropical clawed frog frmd8 (60% identical), zebrafish frmd8 (55% identical), Drosophila melanogaster Bili (32% identical), Caenorhabditis elegans frm-10 (20% identical). Paralogues in human: KRIT1 (20% identical).
Diseases named in the same sentence as FRMD8 in open-access papers:
FRMD8 is named in the same sentence as 15 diseases in open-access papers, as found by Europe PMC text mining. Sharing a sentence is not in itself a finding about the gene and the disease. The quoted sentences say what the papers report.
breast carcinoma (2 papers, 2024 to 2025). "Taken together, these findings demonstrated that loss of Frmd8 accelerates mammary tumor growth and generates resistance to tamoxifen therapy in Frmd8-depleted mice." (PMID 40213945, 2025). "In this study, we found that loss of Frmd8 in luminal epithelial cells of MMTV-PyMT mice accelerates mammary tumor progression and luminal epithelial phenotype loss, and confers tamoxifen resistance." (PMID 40213945, 2025). "To investigate the mechanism through which Frmd8 loss promotes mammary tumor growth and leads to tamoxifen resistance, we then performed single-cell RNA sequencing (scRNA-seq) analysis." (PMID 40213945, 2025). "We demonstrated that loss of FRMD8 promotes mammary tumor growth, accelerates the loss of mammary luminal phenotype, and confers tamoxifen resistance via downregulating ERα level." (PMID 40213945, 2025). "Moreover, we also found that a decreased FRMD8 level was associated with poor recurrence-free survival in breast cancer patients according to Kaplan–Meier Plotter analysis." (PMID 40213945, 2025). "Since tamoxifen is commonly used for the treatment of ERα+/HER2- breast cancer, we thus investigated whether loss of Frmd8 affects sensitivity of mammary tumors to tamoxifen treatment in mice." (PMID 40213945, 2025). "The loss of Frmd8 reduced the proportion of Hsd epithelial cells and led to a downregulation of ERα and PR expression, implying that Frmd8 deficiency promotes the loss of luminal features in the mammary gland and accelerates mammary tumor progression." (PMID 40213945, 2025). "Loss of Frmd8 promotes mammary tumor growth and generates tamoxifen resistance in vivo." (PMID 40213945, 2025). "To this end, we transiently transfect Flag-FRMD8 vector or FRMD8 siRNA in human breast cancer cells." (PMID 40213945, 2025). "To further investigate the clinical significance of FRMD8 in breast cancer patients, we performed immunohistochemical staining of FRMD8 in a tissue microarray of breast cancer patients and evaluated the level of FRMD8." (PMID 40213945, 2025). "(G) Kaplan–Meier analysis for the overall survival of breast cancer patients according to FRMD8 expression (Log-rank test)." (PMID 40213945, 2025). "In breast cancer patients, FRMD8 gene promoter is found hypermethylated and low level of FRMD8 predicts poor prognosis." (PMID 40213945, 2025). "The results showed that 5-Aza-dC treatment significantly upregulated both mRNA and protein levels of FRMD8 in claudin-low but not luminal breast cancer cell lines, which was consistent with the lower expression of FRMD8 in claudin-low breast cancer cell lines." (PMID 40213945, 2025). "Representative examples (scale bar, 100 μm) of normal tissue adjacent to tumor and breast cancer with different levels of FRMD8 expression are shown, with the magnification of selected areas inserted." (PMID 40213945, 2025). "Collectively, these data indicated that the promoter of FRMD8 is hypermethylated, and the low FRMD8 level predicts poor prognosis of breast cancer patients." (PMID 40213945, 2025). "Results showed that FRMD8 expression was lower in claudin-low breast cancer cell lines compared with normal mammary epithelial cell line or ERα-positive cell lines." (PMID 40213945, 2025). "FRMD8 deficiency in MMTV-Cre+; Frmd8fl/fl; PyMT mice accelerates mammary tumor growth and loss of luminal phenotype, and confers tamoxifen resistance." (PMID 40213945, 2025). "Compared with MMTV-Cre-; Frmd8fl/fl; PyMT mice, Frmd8 depleted in mice significantly promotes mammary tumor development." (PMID 40213945, 2025). "Single-cell RNA profiling reveals that the number of hormone-sensing differentiated cells is diminished and the level of ERα is decreased in Frmd8-knocked-out mammary tumors." (PMID 40213945, 2025). "In this study, our results suggested that FRMD8 inhibits mammary tumor progression in MMTV-PyMT mice." (PMID 40213945, 2025).
breast carcinoma (continued). "ScRNA-seq results demonstrated that the level of Frmd8 in normal Hsd epithelial cells was significantly higher than other tumor cells in the mammary tumors from PyMT mice." (PMID 40213945, 2025). "Thus, we demonstrated that FRMD8 is an important ERα regulator and a vital tumor suppressive protein in breast cancer growth and drug resistance." (PMID 40213945, 2025). "Further, a low FRMD8 level predicts poor prognosis in human breast cancer patients." (PMID 40213945, 2025). "In this study, we found that FRMD8 plays a tumor suppressive role in breast cancer progression." (PMID 40213945, 2025). "FOXO3A suppresses breast cancer stem cell properties and tumorigenicity via inhibition of FOXM1/SOX2 signaling, suggesting that FRMD8 may have an effect on breast cancer stem cells." (PMID 40213945, 2025). "Moreover, the promoter of FRMD8 is hypermethylated and a decreased FRMD8 level predicts poor outcomes in breast cancer patients." (PMID 40213945, 2025). "It was known that the common endocrine treatment for non-metastatic breast cancer relies on the expression of ERα, and our results demonstrated that loss of Frmd8 promotes mammary tumor growth and confers tamoxifen resistance in mice." (PMID 40213945, 2025). "(F) IHC analysis of FRMD8 expression in human breast carcinoma TMA was performed." (PMID 40213945, 2025). "FRMD8 promoter is methylated and low FRMD8 level predicts poor prognosis in breast cancer patients." (PMID 40213945, 2025). "In summary, we identified FRMD8 as a prognostic marker in breast cancer." (PMID 40213945, 2025). "Given that Frmd8 prevents mammary tumor growth and inhibits tumor cell proliferation in mice, we would like to investigate whether the expression of FRMD8 is downregulated in mammary tumors." (PMID 40213945, 2025). "In addition, we observed that loss of Frmd8 significantly decreased the expression of Esr1 and Pgr in normal cells of mammary tumors and decreased expression of Frmd8 in tumor cells accompanied with low expression of Esr1 and Pgr compared with normal cells." (PMID 40213945, 2025). "Furthermore, immunohistochemical staining showed that the percentage of Ki67-positive cells was significantly elevated in mammary tumors of Frmd8-depleted mice." (PMID 40213945, 2025). "Therefore, FRMD8 is an important regulator of ERα and may control therapeutic sensitivity to tamoxifen in ERα-positive breast cancer patients." (PMID 40213945, 2025). "Therefore, we investigated whether the promoter region of FRMD8 is hypermethylated in breast cancer patients." (PMID 40213945, 2025). "ATG2A exhibits mutations in breast cancer, FRMD8 plays a tumor-suppressive role in breast cancer progression, ARSG is negatively correlated with positive prognosis, and differentially expressed genes upregulated by SAC3D1 are involved in regulating the cell cycle pathways in breast cancer cells." (PMID 39720180, 2024).
acute myeloid leukemia (1 paper, 2023). Acute myeloid leukemia (AML) is a group of neoplasms arising from precursor cells committed to the myeloid cell-line differentiation. "Moreover, amplifications in iTAP/FRMD8 copy number have been observed in pediatric acute myeloid leukemia patients, particularly within the context of primary chemotherapy resistance." (PMID 36720499, 2023).
breast tumors (1 paper, 2025). "An analysis based on the TCGA database showed that the FRMD8 promoter was highly methylated in primary breast tumors." (PMID 40213945, 2025).
colitis (1 paper, 2023). Inflammation of the colon. "Our data hence establish that like ADAM17, loss of iTAP/Frmd8 exacerbates experimental colitis in vivo and impairs the capacity of recovery after the insult." (PMID 36720499, 2023). "Consistent with this ADAM17 phenotype, iTAP/Frmd8 KO mice were more prone to worsened indicators of disease triggered by a model of acute DSS-induced colitis, including more pronounced body weight loss and colon shortening." (PMID 36720499, 2023). "To address the effect of iTAP/Frmd8 loss on epithelial repair capacity after the DSS insult, we induced colitis but let the mice recover for 5 d after DSS exposure." (PMID 36720499, 2023). "Consistent with this notion, ADAM17ex/ex mice are more profoundly sensitized to DSS-induced colitis than appears to be the case in iTAP/Frmd8 KO mice, suggesting that the titer of mature ADAM17 available may be higher in iTAP/Frmd8 KO mice than in ADAM17ex/ex mice." (PMID 36720499, 2023). "Interestingly, unlike our observed sensitization of iTAP/Frmd8 KO mice to DSS-triggered colitis, it has been shown that iRhom2 KO mice are not sensitized to DSS-induced colitis." (PMID 36720499, 2023).
lung carcinoma (1 paper, 2025). "FRMD8 regulates lung cancer cell growth by regulating tumor microenvironment." (PMID 40213945, 2025).
myelodysplastic syndrome (1 paper, 2023). A clonal hematopoietic disorder characterized by dysplasia and ineffective hematopoiesis in one or more of the hematopoietic cell lines. "This includes the preleukemic condition myelodysplastic syndrome, where iTAP/FRMD8 mutations have been found in patient clones after chemotherapy." (PMID 36720499, 2023).
myeloid malignancies (1 paper, 2023). "Interestingly, mutations or copy-number variations within the iTAP/FRMD8 gene have been reported in clones isolated from patients suffering from myeloid malignancies." (PMID 36720499, 2023). "It will be interesting to determine, in future studies, whether regulation of the sheddase complex underpins the association between iTAP/Frmd8 and poor disease prognosis, or whether iTAP/Frmd8 regulates additional pathways within the context of myeloid malignancies." (PMID 36720499, 2023).
Sepsis (1 paper, 2023). Sepsis is defined as life-threatening organ dysfunction caused by a dysregulated host response to infection. "To probe this observation in an in vivo context, we challenged iTAP/Frmd8 KO mice in a sepsis model driven by i.p. administration of LPS." (PMID 36720499, 2023).
tumor (7 papers, 2021 to 2026). "Since the expression of ERα is loss with tumor progression, to further clarify the regulation of Frmd8 on ERα, we performed immunohistochemistry (IHC) staining of mammary glands of 7-week-old PyMT mice, which had no palpable tumors." (PMID 40213945, 2025). "In this model, loss of iTAP/Frmd8 significantly reduced the number of lung tumors, and the tumor volume and burden compared with parental WT cells." (PMID 36720499, 2023). "The results also showed that the expression of Frmd8 was decreased in tumor cells compared with normal cells." (PMID 40213945, 2025). "(L) Statistical analysis of Frmd8, Esr1 and Pgr expression in normal and tumor cells from MMTV-Cre-; Frmd8fl/fl; PyMT and MMTV-Cre+; Frmd8fl/fl; PyMT mice." (PMID 40213945, 2025). "(K) Dot plot showing the expression of Frmd8 in normal and tumor cells from MMTV-Cre-; Frmd8fl/fl; PyMT and MMTV-Cre+; Frmd8fl/fl; PyMT mice." (PMID 40213945, 2025). "As our results indicate that iTAP/Frmd8 can promote LLC tumor cell growth and proliferation, we turned to simpler in vitro models to explore this effect." (PMID 36720499, 2023). "Taken together, our data reveal that iTAP/Frmd8 expression in the tumor microenvironment promotes tumor growth." (PMID 36720499, 2023). "Strikingly, we found that iTAP/Frmd8 KO host mice were protected from tumor growth, resulting in tumors of a lower volume and mass." (PMID 36720499, 2023). "As ADAM17 maturation is decreased in multiple tissues of iTAP/Frmd8 KO mice, including the lung, and defects in its sheddase activity were observed in ex vivo and in in vivo experiments, we next evaluated the effect of iTAP/Frmd8 depletion on tumor growth and metastasis." (PMID 36720499, 2023). "Having observed that iTAP/Frmd8 expression in recipient host mice affects WT LLC tumor cell growth in vivo, we next assessed whether cell-autonomous iTAP/Frmd8 expression influences LLC tumor cell growth, this time in WT immunocompetent recipient mice." (PMID 36720499, 2023). "Furthermore, we show that iTAP/Frmd8 regulates cancer cell growth in a cell-autonomous manner and by modulating the tumor microenvironment." (PMID 36720499, 2023). "We next tested the impact of these cells when injected subcutaneously into immunocompetent WT mice, finding that the local tumors in the mice that received the iTAP/Frmd8 KO cells had a reduced growth rate, leading to smaller tumor volume and mass compared with parental controls." (PMID 36720499, 2023). "Our study also establishes that iTAP/Frmd8 expression can influence multiple aspects of tumor growth and dissemination: it conditions the host microenvironment to promote tumor growth, while also influencing cell-autonomous tumor growth and dissemination." (PMID 36720499, 2023). "Additionally, FRMD8 expressions in both microenvironment and tumor cells promote lung tumor growth." (PMID 40213945, 2025). "FRMD8highERαhigh and FRMD8highPRhigh cells were mainly present in normal tissues adjacent to tumor of MMTV-Cre-; Frmd8fl/fl; PyMT mice, whereas Frmd8 depletion led to FRMD8lowERαlow and FRMD8lowPRlow cells markedly increased." (PMID 40213945, 2025). "The genes that appeared most frequently among the top projected targets for the 15 patient tumor samples were SLC24A1, ARTN, DHRSX, TEX261, and FRMD8." (PMID 34662337, 2021). "Immunohistochemical analyses further confirmed increased protein expression of representative risk-associated genes, including pannexin 1 (PANX1) and FERM domain containing 8 (FRMD8), in multiple tumor tissues compared with corresponding normal tissues." (PMID 41898689, 2026). "The FERM domain protein iTAP/Frmd8, which binds to and stabilizes the ADAM17/iRhom sheddase complex at the cell surface, is a regulator of inflammation, epithelial homeostasis, and tumor growth in vivo." (PMID 36720499, 2023).
cancer (1 paper, 2023). A tumor composed of atypical neoplastic, often pleomorphic cells that invade other tissues. "Our work identifies that intervention at the level of iTAP/Frmd8 may be beneficial to target the inflammatory features of ADAM17 associated with iRhom2, and shows new insights of the iTAP/Frmd8-mediated sheddase complex on cancer growth regulation." (PMID 36720499, 2023). "With this in mind, the targeting of iTAP/Frmd8 may be an appealing potential strategy to target ADAM17 activity in specific compartments during chronic inflammatory diseases or cancer, while avoiding collateral impact on the vital functions of ADAM17 in normal tissues." (PMID 36720499, 2023).
FRMD8 also shares sentences with these, for which no sentence is quoted: Alzheimer disease (2 papers); COVID-19 (1); leprosy (1); Lewis lung carcinoma (1); triple-negative breast carcinoma (1).